ALOX5AP (arachidonate 5-lipoxygenase activating protein)
Diseases named in the same sentence as ALOX5AP in open-access papers (continued):
Sharing a sentence is not in itself a finding about the gene and the disease.
breast carcinoma (10 papers, 2013 to 2025). "In this study, we identified several SNPs in the ALOX5 and ALOX5AP genes that showed associations with overall breast cancer risk and differences by menopausal and ER status, in either White or Black women." (PMID 34249719, 2021). "For instance, ALOX5AP mRNA was aberrantly expressed and associated with poor prognosis in breast cancer, and inhibiting ALOX5AP activity attenuated breast cancer cell growth." (PMID 34094977, 2021). "The ALOX5-rs7099874 and ALOX5AP-rs9579648 were specifically associated risk of ER+ breast cancer, while ALOX5AP-rs9315048 were associated with risk of ER− cancer, in either White or Black women." (PMID 34249719, 2021). "In a previous report, we examined the genetic expression of COX1, COX2, ALOX5 and ALOX5AP in breast cancer specimens from TCGA." (PMID 37190308, 2023). "A number of these SNPs in COX2, ALOX5, ALOX5AP, and ALOX12 genes were found to be associated with overall breast cancer risk, as well as breast cancer risk in subgroups defined by menopausal and ER status, in either White or Black women." (PMID 34249719, 2021). "Apart from KL and PARP4, the 13q linkage peak also includes known candidate genes for inflammation, e.g., arachidonate 5-lipoxygenase-activating protein (ALOX5AP), and cancer, e.g., breast cancer 2 early onset (BRCA2), all of which may be involved in the aging process." (PMID 24036517, 2013). "The activation of ALOX5AP (Arachidonate 5-lipoxygenase activating protein) correlates with the HER2 (human epidermal growth factor receptor 2) and promotes the growth and migration of breast cancer." (PMID 34484333, 2021). "In contrast, HER2 inhibition led to decreased expression and activity of ALOX5 but not ALOX5AP, suggesting that HER2 specifically regulates the ALOX5 expression and activity in breast cancer cells." (PMID 33224971, 2020).
Obesity (8 papers, 2013 to 2024). Accumulation of substantial excess body fat. "The expression of ALOX5AP has also been found associated with obesity and insulin resistance as well as exercise-induced stress." (PMID 34795690, 2021). "Five genes map to the common CNV interval, among them ALOX5AP whose expression was linked to obesity and insulin resistance." (PMID 29441128, 2018). "ALOX5AP is also associated with obesity and insulin resistance, which may make a connection between adipose tissue, inflammation, and insulin resistance." (PMID 39479394, 2024). "Among the genes, we highlighted the Irf5, which is negatively correlated with insulin sensitivity and obesity, and Alox5ap, which signals adipose tissue inflammation and lipid dysfunction in adipose tissue of obese mice." (PMID 32906847, 2020). "Our findings implicate many genes previously associated with obesity (e.g. PTBP2, TMEM18, MYT1L, POU3F2, SIM1, SH2B1), and also identified other potentially relevant candidates including TAS1R3, ALOX5AP, and GAS6." (PMID 29441128, 2018). "Our results showed that ALOX5AP was upregulated in obesity compared to lean and post-RYGB, suggesting that its downregulation, starting at 1-year and maintained up to 5-years post-RYGB, could be responsible for a better AT functionality." (PMID 36432612, 2022). "Previous studies confirmed that ALOX5AP overexpression in mouse adipose tissue leads to lipoxin A4 (LXA4) production and diet-induced obesity." (PMID 30886630, 2019).
coronary artery disease (7 papers, 2010 to 2025). "A study found that ALOX5AP gene variation is associated with interindividual differences in the risk of coronary artery disease." (PMID 39479394, 2024).
glioma (7 papers, 2020 to 2025). A benign or malignant brain and spinal cord tumor that arises from glial cells (astrocytes, oligodendrocytes, ependymal cells). "In GBM tumors, there is elevated expression of 5-LOX/ALOX5 and FLAP/ALOX5AP relative to healthy brain tissue, which is similar to lower grade gliomas." (PMID 36765904, 2023). "This indicates that the elevated expressions of 5-LOX/ALOX5 and FLAP/ALOX5AP may be glioma-specific." (PMID 36765904, 2023). "The Macro index comprised of PIK3R5, PIK3R6, ALOX5, ALOX5AP, and ALOX15B serves as a valid prognostic biomarker for gliomas, especially LGG." (PMID 36159811, 2022). "The mRNA expression of APOBEC3C, FCGRT, GNG5, and SP100 was elevated in glioma, whereas the expression of ADAP2, ALOX5AP, and LRRC25 was low." (PMID 32431729, 2020).
Insulin resistance (7 papers, 2014 to 2024). Increased resistance towards insulin, that is, diminished effectiveness of insulin in reducing blood glucose levels. "Genes with a positive association with inflammation, chemotaxis, insulin resistance, and inflammatory cell death, such as Irf5, Alox5ap, Tlrs, Cd84, Ccr5, Ccl9, and Casp1, were downregulated by EPA." (PMID 32906847, 2020). "Subcutaneous adipose tissue expression of ALOX5AP has previously been shown to be positively associated to body weight and insulin resistance as determined by HOMA-IR index." (PMID 26378572, 2015).
osteosarcoma (6 papers, 2019 to 2025). A usually aggressive malignant bone-forming mesenchymal neoplasm, predominantly affecting adolescents and young adults. "Additionally, ALOX5AP also involved in a risk model to serve as a prediction of osteosarcoma metastasis." (PMID 32431729, 2020). "A combination of eight genes (RAB1,CLEC3B,FCGBP,RNASE3,MDL1,ALOX5AP,VMO1 and ALPK3) were identified as being associated with osteosarcoma metastasis." (PMID 30868060, 2019). "Hence, I have compared the prognostic gene set for osteosarcoma, Cox univariate and multivariate analysis showed that BACE2, ING2 ALOX5AP, HLA-DMB, HLA-DRA, and SPINT2 were not the independent prognostic factors for osteosarcoma." (PMID 33520450, 2021).
colorectal cancer (5 papers, 2020 to 2025). A primary or metastatic malignant neoplasm that affects the colon or rectum. "Tumor-promoting genes highly correlated with the expression of COX1, COX2, ALOX5 and ALOX5AP are known to increase mitogenesis, mutagenesis, angiogenesis, cell survival, immunosuppression and metastasis in the inflammogenesis of colorectal cancer." (PMID 37190308, 2023). "Our results confirm that COX1, COX2, ALOX5 and ALOX5AP, rate-limiting enzymes of prostaglandin and leukotriene biosynthesis, are all constitutively expressed in colorectal cancer." (PMID 37190308, 2023). "In the current study, we examined the expression of COX1, COX2, ALOX5, ALOX5AP and related genes in surgical specimens of colorectal cancer ascertained from The Cancer Genome Atlas (TCGA)." (PMID 37190308, 2023). "We examined the expression of major inflammatory genes, cyclooxygenase-1, 2 (COX1, COX2), arachidonate-5-lipoxygenase (ALOX5), and arachidonate-5-lipoxygenase activating protein (ALOX5AP) among 469 tumor specimens of colorectal cancer in The Cancer Genome Atlas (TCGA)." (PMID 37190308, 2023).
COVID-19 (5 papers, 2020 to 2025). A disease caused by infection with severe acute respiratory syndrome coronavirus 2. "Taken together with the HLA-B*40:01 restricted binding of the PAM and ANXA7 peptides mimicked by SARS-CoV-2, the ALOX5AP splicing variant also mimicked by SARS-CoV-2 suggests the possibility of immune evasion or autoinflammation in HLA-B*40-constrained COVID-19 patients." (PMID 33024578, 2020). "Congruently, increased ALOX5 activity and ALOX5AP expression are observed in bronchoalveolar lavage (BAL) neutrophils in critical COVID-19 patients." (PMID 36143338, 2022). "If several evidences confirm that a hyperinflammatory signature characterizes monocytes from COVID-19 patients, other data prove that an immunosuppressive signature, defined by downregulation of HLA-DRA, ALOX5AP, and RETN, also exists." (PMID 35710943, 2022). "Increased expression of ALOX5AP, ALOX5, and plasma LTB4 are also noted in diabetic COVID-19 cases requiring intensive care." (PMID 36143338, 2022).
ovarian carcinoma (5 papers, 2019 to 2023). A malignant neoplasm originating from the surface ovarian epithelium. "In this study, compared to other cancer types, in ovarian cancer most of the immunosuppressive hallmarks were significantly positively associated with ALOX5AP expression." (PMID 34094977, 2021). "ALOX5AP exhibited significant expression in the immunoreactive subtype of ovarian cancer, and its expression was directly correlated with immunocyte infiltration, particularly the polarization of M2 macrophages." (PMID 37344882, 2023). "Concordant with the previous results, the ovarian cancer samples expressed significantly more ALOX5AP than the normal controls (fold change: 3.28, p = 0.0172)." (PMID 34094977, 2021). "Among them, TIM3, which had the highest Spearman correlation r value with ALOX5AP, has been reported to negatively regulate antitumor immunity by inducing active T cell exhaustion and exerting an antiproliferative effect in the ovarian cancer TME." (PMID 34094977, 2021). "Further exploration demonstrated that ALOX5AP was highly expressed in the immunoreactive subtype of ovarian cancer and closely related to immunocyte infiltration, especially M2 macrophage polarization." (PMID 34094977, 2021). "We next utilized the TISIDB database to estimate the relationship between ALOX5AP and several well-known immune suppressive molecules in the ovarian cancer microenvironment." (PMID 34094977, 2021). "To further verify the prognostic significance of ALOX5AP, we assessed another three independent ovarian cancer microarray datasets (GSE9891, GSE14764, and GSE30161)." (PMID 34094977, 2021). "Another study found the transcription levels of 5-LOX and ALOX5AP in ovarian cancer cell lines were increased under hypoxic conditions." (PMID 34094977, 2021). "ALOX5AP expression patterns across ovarian cancer and their normal tissue counterparts were cross-checked using public microarray and RNA-seq analyses and then validated in clinical samples by qRT-PCR." (PMID 34094977, 2021). "Although this study improved our understanding of the oncogenic role of ALOX5AP in ovarian cancer progression and development, there were several limitations." (PMID 34094977, 2021). "To gain insight into the functional role of ALOX5AP in ovarian cancer, we performed several enrichment assays." (PMID 34094977, 2021). "All dataset evaluations indicated that increased ALOX5AP mRNA levels were significantly associated with poor OS and PFS in ovarian cancer patients." (PMID 34094977, 2021). "The results strongly implicate ALOX5AP as a possible co-contributor to immune evasion in the ovarian cancer immune microenvironment." (PMID 34094977, 2021). "It is therefore probable that ALOX5AP has close relationship with inflammation and immune regulation and ultimately, the ovarian cancer microenvironment." (PMID 34094977, 2021). "We thereby concluded that elevated ALOX5AP expression was a strong predictor for worse prognosis among ovarian cancer patients." (PMID 34094977, 2021). "We found that ALOX5AP could be exploited as a prognostic predictor and therapeutic target via its effect on the ovarian cancer immune microenvironment." (PMID 34094977, 2021). "Herein, using the valuable and reliable information provided by the open high-throughput transcriptomic database, we applied a series of bioinformatics algorithms to cross-check the expression and prognostic role of ALOX5AP across multiple independent ovarian cancer patient cohorts." (PMID 34094977, 2021). "However, few studies on ALOX5AP and its potential role in ovarian cancer carcinogenesis have been reported." (PMID 34094977, 2021). "Intriguingly, the heatmap revealed that ALOX5AP was positively correlated with an abundance of immune inhibitors in ovarian cancer, compared to other cancer types, suggesting that ALOX5AP may have a potential to serve as an immunotherapy target in SOC." (PMID 34094977, 2021).
ovarian carcinoma (continued). "This sex bias suggests that ovarian cancer patients may benefit from superior efficacy and reduced side effects when treated with ALOX5AP inhibitors." (PMID 34094977, 2021). "ALOX5AP may serve as a useful adjunct target in future immune checkpoint inhibitor ovarian cancer treatment." (PMID 34094977, 2021). "Additionally, we assessed survival rate of correlation to ALOX5AP based on different ovarian cancer stages, we found that elevated ALOX5AP expression significantly predicted worse OS and PFS in stage 3-4 patients (p < 0.05) but not in stage 1-2 patients (p > 0.05; data not shown)." (PMID 34094977, 2021). "One exciting but reasonable speculation is that combining immune-checkpoint blockade and ALOX5AP inhibitor therapies could synergistically halt ovarian cancer progression by simultaneously combating M2 macrophage infiltration and immune suppression in the ovarian cancer microenvironment." (PMID 34094977, 2021). "Although much known about the function of 5-LOX in ovarian cancer, ALOX5AP is no less important, given that ALOX5AP is critical in activating 5-LOX function." (PMID 34094977, 2021). "Notably, our study found that crucial immune repressive receptors—which have gained significant attention in ovarian cancer research, such as TIM3, CSF1R, CTLA4, PD1, and LAG3 as well as inhibitory enzymes such as IDO1—were closely related to ALOX5AP expression." (PMID 34094977, 2021).
Alzheimer disease (4 papers, 2014 to 2024). A progressive, neurodegenerative disease characterized by loss of function and death of nerve cells in several areas of the brain leading to loss of cognitive function such as memory and language. "Here, Alox5 (the gene encoding 5-Lox) and Alox5AP (the gene encoding FLAP) expression is predominantly expressed in microglia, in particular in Alzheimer’s disease brains." (PMID 37600518, 2023).
Sepsis (4 papers, 2020 to 2025). Sepsis is defined as life-threatening organ dysfunction caused by a dysregulated host response to infection. "An in-depth analysis of the patient cohorts revealed that in sepsis, the mRNA encoding ALOX5AP is upregulated and persists over a period of at least seven days of the ICU stay." (PMID 31906585, 2020). "A recent study used single cell RNA sequencing to reveal a CD14+ monocyte phenotype named MS1, characterized by high expression of RETN, ALOX5AP, and IL1R2, that was unique in patients with sepsis and associated with sepsis-induced immunosuppression." (PMID 36470832, 2022). "Focusing on 55 highly variable genes selected for further investigation, arachidonate 5-lipoxygenase-activating protein (ALOX5AP) was highly upregulated in monocytes of ICU patients and only normalized during 7 days in the ICU in non-sepsis patients." (PMID 31906585, 2020). "Furthermore, even after seven days in the ICU, patients with sepsis failed to restore ALOX5AP mRNA expression to baseline conditions, unlike patients with excluded sepsis." (PMID 31906585, 2020). "Moreover, longitudinal analyses on days 1, 3, and 7 of the ICU stay revealed a normalization of ALOX5AP mRNA expression from non-septic patients towards the expression level of healthy individuals, whereas the mRNA levels from patients with sepsis remained elevated." (PMID 31906585, 2020).
diabetes (3 papers, 2016 to 2024). "In diabetes, the tubulointerstitium and glomeruli of kidney tissue demonstrated upregulation of ALOX5 and ALOX5AP, and mostly downregulation of COX genes." (PMID 39062733, 2024).
leukemia (3 papers, 2020 to 2023). A malignant (clonal) hematologic disorder, involving hematopoietic stem cells and characterized by the presence of primitive or atypical myeloid or lymphoid cells in the bone marrow and the blood. "MicroRNAs positively associated with ALOX5AP expressions, such as miR125b, miR-93, miR-494, and miR-193b, acted as oncogenes in leukemia." (PMID 37994961, 2023). "The change in ALOX5AP expression can cause oxidative stress, which has some effects on human leukemia." (PMID 31992246, 2020). "Alox5ap has been identified as specifically upregulated in leukemia stem cells and unchanged in hematopoietic stem cells, indicating specificity in cancer cell self-renewal and differentiation." (PMID 34315405, 2021). "It was therefore reasonable to speculate that overexpression of ALOX5AP may contribute to the activation of the Wnt pathway and enhancement of leukaemia cell proliferation." (PMID 37994961, 2023).
serous ovarian cancer (3 papers, 2021 to 2024). "In different serous ovarian cancer patient cohorts, an elevated level of ALOX5AP was significantly related not only to a lower overall survival and progression-free survival, but also to unfavorable clinicopathological characteristics." (PMID 37344882, 2023).
acute coronary syndrome (2 papers, 2008 to 2014). Signs and symptoms related to acute ischemia of the myocardium secondary to coronary artery disease. "We investigated the relationships between the ALOX5AP gene rs10507391 and rs4769874 polymorphisms, serum levels of leukotriene (LT) B4, and risk of acute coronary syndrome (ACS)." (PMID 25210744, 2014).
cerebral infarction (2 papers, 2012 to 2020). An ischemic condition of the brain, producing a persistent focal neurological deficit in the area of distribution of the cerebral arteries. "The findings suggest that SNP rs4073259 of the ALOX5AP gene is associated with developing cerebral infarction in this cohort, although the possibility that it is a functional variant cannot be ruled out." (PMID 22849376, 2012). "The association between the genetic polymorphism of ALOX5AP and the occurrence of cerebral infarction has been previously reported, but discrepancies between studies carried out in different populations have been noted." (PMID 22849376, 2012). "However, more studies with large sample size are needed to detect the extended haplotype, and further confirm whether other SNPs of the ALOX5AP gene are associated with cerebral infarction." (PMID 22849376, 2012).
esophageal squamous cell carcinoma (2 papers, 2019 to 2020). Esophageal squamous cell carcinoma (ESCC) is a type of esophageal carcinoma (EC) that can affect any part of the esophagus, but is usually located in the upper or middle third. "Moreover, the expression levels of ALOX5AP are significantly correlated with the survival time of esophageal squamous cell carcinoma patients." (PMID 30868060, 2019).
nasal polyp (2 papers, 2021 to 2022). "Expression levels of ALOX5AP, AQP9, CCL13, EMR3, F13A1, GAPT, and NCF2 were significantly higher in nasal polyp samples from ACRSwNP patients compared with the expression levels in samples from healthy subjects." (PMID 36059464, 2022). "Next, we identified the protein level of the seven hub genes (ALOX5AP, BCL2A1, BTK, CYBB, NCF2, HCK, and HK3) from nasal polyps from CRSwNPs and nasal mucosa from healthy controls." (PMID 33603773, 2021). "We found that ALOX5AP, BCL2A1, BTK, CYBB, NCF2, HCK, and HK3 were broadly expressed on both epithelial layer and stromal layer in nasal polyp tissues." (PMID 33603773, 2021). "The western blot results showed the expression level of ALOX5AP, BTK, CYBB, NCF2, HCK, and HK3 in CRSwNP was significantly increased in nasal polyps compared to control subjects." (PMID 33603773, 2021). "Our study has proved the increased expression of ALOX5AP, BCL2A1, BTK, CYBB, NCF2, HCK, and HK3 by mRNA and protein levels in nasal polyps." (PMID 33603773, 2021). "Moreover, the immunohistochemistry stain results also demonstrated that the protein level of ALOX5AP, BCL2A1, BTK, CYBB, NCF2, HCK, and HK3 were significantly increased in nasal polyps compared to control subjects." (PMID 33603773, 2021).
acute myeloid leukemia (1 paper, 2023). Acute myeloid leukemia (AML) is a group of neoplasms arising from precursor cells committed to the myeloid cell-line differentiation. "Moreover, the increased expression of ALOX5AP was also found in cytogenetically normal acute myeloid leukemia (CN-AML) patients (P = 0.0144)." (PMID 37994961, 2023).